CD34 (CD34 molecule)
Diseases named in the same sentence as CD34 in open-access papers (continued):
Sharing a sentence is not in itself a finding about the gene and the disease.
Wiskott-Aldrich syndrome (5 papers, 2011 to 2021). Wiskott-Aldrich syndrome (WAS) is a primary immunodeficiency disease characterized by microthrombocytopenia, eczema, infections and an increased risk for autoimmune manifestations and malignancies. "The authors tracked CD34+ cells (isolation from BM and PB) over time in patients who received gene therapies for Wiskott-Aldrich syndrome (WAS), sickle cell disease (βS/βS) and thalassemia (β0/βE)." (PMID 35011669, 2021). "In a phase 1/2 clinical study, autologous CD34+ cells genetically modified with a lentiviral vector encoding for human WAS cDNA12, 14 were re-infused to patients with severe Wiskott-Aldrich syndrome after a reduced-intensity conditioning regimen." (PMID 30981783, 2019). "Studies in a larger cohort of patients are needed to establish if ex-vivo gene-corrected CD34+ cells from mobilised peripheral blood and bone marrow differ in their biological properties and capacity to restore haemopoiesis after gene therapy for Wiskott-Aldrich syndrome." (PMID 30981783, 2019). "In the most recent gene therapy trial for Wiskott-Aldrich Syndrome (WAS) an MLV-based vector backbone expressing the WAS protein was used for transduction of autologous CD34+ HSC which were transfused into two patients." (PMID 21994741, 2011). "The LAM-PCR protocol was used to determine the integration site profile of retroviral-based vectors within the genome of CD34+ hematopoietic stem cells of two patients with Wiskott-Aldrich syndrome (WAS), who participated in a phase I gene therapy clinical trial." (PMID 23209944, 2012).
abdominal aortic aneurysm (4 papers, 2015 to 2025). Enlargement and ballooning of the vessel that supplies arterial blood to the abdomen, pelvis and legs. "In these studies, they generally investigated CD34+/CD133+ cellsin abdominal aortic aneurysm (AAA) and CD34+/CD309 + cells in ascending aorticaneurysm." (PMID 35072395, 2022). "However, the role of CD34+ cells in abdominal aortic aneurysm (AAA) remains unclear." (PMID 39731355, 2025).
acute kidney injury (4 papers, 2015 to 2025). Sudden and sustained deterioration of the kidney function characterized by decreased glomerular filtration rate, increased serum creatinine or oliguria. "Notably, autologous peripheral blood-derived CD34+ cell administration was reported to substantially improve severe, acute renal failure in a patient with malignant hypertension who was once dependent on dialysis." (PMID 41294818, 2025). "Boosting peripheral CD34-positive cells (after cyclophosphamide and GCSF treatment) failed to exert any renoprotective effects but rather was associated with greatly increased severity of renal failure as well as increased mortality." (PMID 25389045, 2015). "In addition to acute kidney injury, CD34+ cell therapy may treat chronic kidney injury." (PMID 41294818, 2025).
acute monoblastic leukemia (4 papers, 2012 to 2025). "Immunophenotypic analysis of the bone marrow showed expression of CD11b, CD13, CD14, CD15, CD33, CD34, CD45 and human leukocyte antigen-DR, findings compatible with the diagnosis of acute monoblastic leukemia (French-American-British classification M5a)." (PMID 22339850, 2012). "KMT2A-rearranged acute monoblastic leukemia is usually negative for CD34; however, this neoplasm case falls within the uncommon 5% of cases that demonstrate CD34 positivity." (PMID 40149468, 2025). "Indeed, acute monoblastic/monocytic leukemia represents approximately 12% of the AML patients and shows an expression of CD34+ or CD117+ only in 7.7% and 19.8% of cases, respectively." (PMID 35851154, 2022).
bladder cancer (4 papers, 2019 to 2025). "Accordingly, we first stained human bladder cancer sections for CD34, and examined various areas in the surrounding normal part, the periphery of the tumor, and within the tumor mass of the sections." (PMID 34359889, 2021). "At the protein level, CD34 expression on HVUECs was significantly reduced after co-culturing with miR-153-expressing bladder cancer cells compared to control HVUECs." (PMID 31355138, 2019).
blood disease (4 papers, 2016 to 2021). A disease that occurs in the blood. "Human CD34+ cells are used in all current stem cell transplantation protocols for blood diseases, but they are known to be a heterogeneous collection of hematopoietic progenitors and rare LT-HSCs (so called HSCs;<0.5% of total nucleated bone marrow cells)." (PMID 28871148, 2017). "CD34+ cells, including LT-HSCs, are readily obtainable at a clinical scale and are currently used in all stem cell transplantation protocols for blood diseases." (PMID 28871148, 2017). "Hematopoietic CD34+ stem cells are widely used in the clinical therapy of complicated blood diseases." (PMID 27765075, 2016). "CD34 antigen is a kind of cell surface glycoprotein belonging to the one-way transmembrane protein family, which is usually regarded as a marker of hematopoietic progenitor cells and has been previously used in cell therapy of various blood diseases." (PMID 34307389, 2021). "Successful transplantation with autologous CD34+ cells in the nonhuman primate model strongly suggests a possible application for treating certain blood diseases." (PMID 31196160, 2019).
bone marrow failure (4 papers, 2016 to 2026). "Moreover, the molecular and cellular markers identified in this review, such as CD34+ cells and telomere length, hold significant potential for understanding the broader implications of bone marrow failure in the context of HIV." (PMID 41559990, 2026).
breast adenocarcinoma (4 papers, 2010 to 2024). "We also use 88 duplicate images of the 64-channel CODEX Human FFPE breast adenocarcinoma and test Mistic on seven channels: Keratin14, FoxP3, CD34, CD8, CD3e, CD68, and perlecan." (PMID 35845830, 2022). "Reverse transcription polymerase chain reaction (RT-PCR) demonstrated the presence of CD34 and CD133 mRNA transcripts in all three WCP samples examined, but not in a breast adenocarcinoma cell line, MCF-7." (PMID 21203434, 2010).
carcinoma in situ (4 papers, 2002 to 2015). "In contrast with normal mammary tissue, the number of CD34 fibrocytes was reduced in the stroma surrounding ducts harboring carcinoma in situ, although capillaries with CD34 reactive endothelia were still detectable adjacent to these ducts." (PMID 23469238, 2013). "Stromal changes as identified immunohistochemically by loss or dramatic increase of CD34 positive fibroblasts and detection of SMA-reactive myofibroblasts were observed mostly around ducts harboring moderately or poorly differentiated in situ carcinoma." (PMID 18384688, 2008). "Stromagenesis, as characterized by an increase in SMA and a decrease in CD34 positive myofibroblasts was observed mostly around ducts harboring high grade in situ carcinoma and to a lesser extent around moderately differentiated DCIS." (PMID 18384688, 2008). "Compared to normal lobules, pure ductal carcinoma in situ exhibited a greater density of CD34+ and CD31+ vessels but a decrease in those that were immunopositive for vWF, indicating a difference in phenotype and in density." (PMID 11953822, 2002). "Others have also described the disappearance of CD34 fibrocytes from in situ carcinoma." (PMID 23469238, 2013).
cardiac hypertrophy (4 papers, 2015 to 2024). "To explore the origin of CD34-derived fibroblasts in cardiac hypertrophy, we established chimeric mice by transplanting bone marrow cells from wild-type ApoE-/- mice into irradiated Cd34-CreERT2;Rosa26-tdTomato-ApoE-/- mice." (PMID 39198543, 2024). "Using scRNA‐seq of murine and human heart tissue, researchers characterized the cellular landscape during heart hypertrophy, focusing on CD34+ cells." (PMID 39159065, 2024). "To delineate the constitution map of cardiac resident CD34 lineage cells during different stages of cardiac hypertrophy, we performed scRNA-seq in CD34 lineage cells (tdTomato+ cells)." (PMID 36805782, 2023). "To analyse the influence of cardiac hypertrophy on migration of BMCs (CD45+/CD34+ cells), we performed flow cytometry of a myocyte-depleted fraction of cardiac cells." (PMID 25754690, 2015). "By analyzing the transcriptomes of 59,505 single cells from the mouse heart and 22,537 single cells from the human heart, we illustrated the dynamics of cell landscape during the progression of heart hypertrophy, including CD34+ cells, fibroblasts, endothelial and immune cells." (PMID 36805782, 2023). "In the bone marrow transplantation of WT to Cd34-CreERT2;Rosa26-tdTomato mice, a large amount of fibroblast markers co-stained with tdTomato, proved that non-bone marrow CD34+ cells are the main source to replenish fibroblast pool in cardiac hypertrophy." (PMID 36805782, 2023). "We next investigated the origin of CD34-derived fibroblast in cardiac hypertrophy." (PMID 36805782, 2023). "The percentage of cluster 1 in CD34+ cell lineage enhanced with the cardiac hypertrophy stages, suggesting that CD34+ cell may be an important source of resident macrophage regeneration." (PMID 36805782, 2023). "G-CSF treatment in mice with cardiac hypertrophy further markedly increased the number of CD45+ CD34+ VLA-4+ cells (3.4-fold; P < 0.01) and CD45+ CD34+ c-kit+ cells (2.8-fold; P < 0.05)." (PMID 25754690, 2015).
Cognitive impairment (4 papers, 2017 to 2026). Abnormal cognition is characterized by deficits in thinking, reasoning, or remembering. "There is also a growing body of evidence to suggest that a reduction in CD34+ progenitor cells is directly related to vascular dysfunction leading to increased BBB permeability, which causes neurotoxicity and, ultimately, cognitive impairment." (PMID 39997032, 2025). "Regarding cognitive impairment, patients with MCI present reduced levels of circulating EPCs as well as CD34+/CD133+ and CD34+ progenitor cells." (PMID 35153724, 2021). "In this study, we examined cognitive deficits in rats subjected to TBI and correlated changes in the number of CD34+ cells and vWF+ vascular cells in the hippocampus of injured brain tissue and EPCs in the peripheral blood." (PMID 29201537, 2017).
colon adenocarcinoma (4 papers, 2017 to 2025). "Additionally, OX40 was positively correlated with the expression of the canonical EC marker genes CD31, VWF, and CD34 in The Cancer Genome Atlas Colon Adenocarcinoma (TCGA-COAD) dataset." (PMID 40026246, 2025). "Repair through granulation tissue and the stromal reaction (repair that does not stop) in adenocarcinoma of the colon are examples of processes that affect adipose tissue with a loss of CD34 expression in TCs/CD34+SCs or the disappearance of these cells." (PMID 33353193, 2020).
depression (4 papers, 2021 to 2026). "Levels of circulating CD34+CD133+KDR+ EPCs and endothelial colony-forming units in patients with depression were lower than that of healthy subjects." (PMID 34421539, 2021). "The number of mature (CD34+ /VEGFR2+) and immature (CD133+/VEGFR2+) EPCs were significantly decreased in depression patients, and EPCs levels was significant inverse relationship with the severity of depressive symptoms." (PMID 34421539, 2021).
endometriosis (4 papers, 2019 to 2025). The growth of functional endometrial tissue in anatomic sites outside the uterine body. "After an integrated and comprehensive analysis, this study shows that the panel of immunomarkers anti-CD20, anti-Tryptase, and anti-CD34 can differentiate periepithelial stroma in endometriosis." (PMID 35628423, 2022). "We found an increased vascularity (CD34+) in the areas with abdominal endometriosis and CD3+−:T-lymphocytes, CD20+−:B-lymphocytes, CD68+:macrophages, and Tryptase+: mastocytes were abundant, especially in cases with adenomyosis as a marker of proinflammatory microenvironment." (PMID 35628423, 2022). "Several proinflammatory/vascular/hormonal changes such as increased expressions of cytokeratin, CD34, CD68+ macrophages, increased Ki67, and inactivation of tumor suppressor genes may trigger endometriosis progression and malignant transformation." (PMID 39768471, 2024).
Fibroadenoma (4 papers, 2016 to 2024). A benign tumor of the breast characterized by the presence of stromal and epithelial elements. "Various markers, including CK18 for luminal cells, α-sma for basal/myoepithelial cells, CD31 for endothelial cells, and CD34 for stromal fibroblasts, were used to distinguish different cellular components in fibroadenoma and phyllodes tumours." (PMID 39767203, 2024). "Because CD34-expressing fibroblasts were observed in both fibroadenoma and PT, efficient treatment for fibroepithelial tumors might be achieved by targeting the fibrous stroma." (PMID 27881889, 2016).
haemophilia A (4 papers, 2013 to 2025). "Currently, a clinical study is evaluating the effectiveness of transplanting autologous CD34+ haematopoietic stem cells transduced with the CD68‐ET3 LV for treating severe haemophilia A (NCT04418414)." (PMID 37199059, 2023).
hepatoblastoma (4 papers, 2017 to 2023). Hepatoblastoma (HB) is a malignant hepatic tumor and is the most common pediatric liver cancer. "Despite these difficulties, we recently identified a CD34+OV-6+CD90+csVimentin+ population in hepatoblastoma cell lines, which showed CSC characteristics and susceptibility to the Hsp90 inhibitor 17-AAG." (PMID 36497307, 2022). "The expression of VEGF, ESM-1, and CD34 was positively associated with CRNDE levels in the hepatoblastoma tissues." (PMID 28178668, 2017). "Previously, we identified a CSC population in hepatoblastoma cell lines expressing the CSC markers CD34 and CD90, cell surface Vimentin (csVimentin) and binding of OV-6." (PMID 36497307, 2022). "In this study, we further explore the characteristics of our recently defined CD34+OV-6+CD90+csVimentin+ hepatoblastoma CSCs." (PMID 36497307, 2022). "Further studies analyzed the expression of CD90 and CD34 in hepatoblastoma specimens using immunohistochemistry and could observe a specific expression of these markers on suggested stem-like cells." (PMID 34685577, 2021). "With our study, we identified CSCs of hepatoblastoma using CD34, CD90, OV-6 and csVimentin." (PMID 34685577, 2021). "Thus, CD34+/lowOV-6lowCD90+ cells represent another subset of hepatoblastoma CSCs." (PMID 36497307, 2022). "We analyzed PD-L1 in hepatoblastoma cell lines and found that our previously investigated CSC population of CD34+/highOV-6highCD90+csVimentin+ cells express PD-L1, whereas non-CSC tumor cells were negative for PD-L1." (PMID 36497307, 2022). "In order to define a set of markers for the identification of CSCs in hepatoblastoma, we analyzed the expression of CD133, CXCR4, CD34 and CD90 in the hepatoblastoma cell lines HepG2 and HuH6 using flow cytometry." (PMID 34685577, 2021). "Here, we present CD34, CD90, OV-6 and cell-surface vimentin (csVimentin) as reliable markers to identify CSCs in hepatoblastoma cell lines." (PMID 34685577, 2021). "Our results showed that the candidates CD133, CXCR4, CD34, CD90 and OV-6 binding were detected at different expression levels in the two investigated hepatoblastoma cell lines (HuH6 and HepG2)." (PMID 34685577, 2021). "In our study, we aimed to investigate the suggested hepatoblastoma CSC markers CD90, CD34 and the OV-6 antibody in two hepatoblastoma cell lines (HuH6 and HepG2)." (PMID 34685577, 2021). "We presented CD34, CD90, OV-6 and csVimentin together as a reliable combination of markers to identify hepatoblastoma CSCs." (PMID 34685577, 2021).
intrahepatic cholangiocarcinoma (4 papers, 2020 to 2025). A carcinoma that arises from the intrahepatic bile duct epithelium in any site of the intrahepatic biliary tree. "Moreover, VG161 efficacy in HLA-matched CD34+ humanized intrahepatic cholangiocarcinoma (ICC) patient-derived xenograft (PDX) models was also tested in multicycle treatment and was compared to standard chemotherapy for this type of cancer (gemcitabine)." (PMID 36366425, 2022). "An association was observed between low FTO expression and high CD34 expression in intrahepatic cholangiocarcinoma (ICC)." (PMID 38053093, 2023).
iron overload (4 papers, 2021 to 2025). "Previous studies have shown that patients with iron overload have significantly lower mobilized CD34+ cell concentrations for autologous transplantation in peripheral blood than those with low ferritin in patients with various hematological malignancies and AML." (PMID 39997353, 2025).
lobular carcinoma (4 papers, 2008 to 2023). "However, one or several extravasated red blood cells could be surrounded by the CD34+SCs/TCs as described for the neoplastic cells of lobular carcinoma of the breast, in which the surrounding CD34+SCs/TCs originate cancer-associated fibroblasts." (PMID 36835203, 2023). "CD34 expression may be preserved in the stromal cells of some epithelial tumours, as occurs in lobular carcinoma of the breast." (PMID 33916213, 2021). "For example, CD34+SCs/TCs are preserved (reactive stromal cells are CD34+) in most lobular carcinoma of the breast, with no transformation into reactive αSMA+ stromal cells." (PMID 33072740, 2020).
Lymphadenopathy (4 papers, 2021 to 2025). Enlargement (swelling) of a lymph node. "Cranial mediastinal lymphadenopathy was present in four out of the five dogs (80%) that expressed CD34, whereas only three of the 18 dogs (16.7%) that did not express CD34 had cranial mediastinal lymphadenopathy." (PMID 37908841, 2023).
lymphoid leukemia (4 papers, 2019 to 2025). A malignant lymphocytic neoplasm of B-cell or T-cell lineage involving primarily the bone marrow and the peripheral blood. "Previous studies have reported that altered TrkA expression in myeloid and lymphoid leukemia provide either a proliferation or a survival advantage to CD34+ hematopoietic cells." (PMID 30808933, 2019). "Additionally, CD276 mRNA was higher in LSCs compared to normal HSCs, and CD34+ cells of acute myeloid and lymphoid leukemia patients had higher CD276 protein expression than their CD34- counterparts." (PMID 40175626, 2025).
lymphoid neoplasm (4 papers, 2017 to 2025). A neoplasm composed of a lymphocytic cell population which is usually malignant (clonal) by molecular genetic and/or immunophenotypic analysis. "Histopathologically, it shows atypical endothelial proliferation with expression of vascular markers CD31, CD34, and factor VIII-related antigen, which help distinguish it from lymphoid neoplasms." (PMID 41227238, 2025).
metastatic carcinoma (4 papers, 2017 to 2023). A carcinoma which has spread from the original site of growth to another anatomic site. "Loss of TRF2 and Terc expression resulted in telomere DNA damage, severely depleted CD34 + and Lgr6+ cancer stem cells, and induced terminal differentiation of metastatic cancer cells." (PMID 29113290, 2017). "Using this method, blood is taken from subjects with metastatic cancer, processed by exclusion of CD45 + cells and capturing of EpCAM + cells in the VERSA, and stained for Hoechst, cytokeratin, and exclusion markers (CD11b, CD45, CD14, CD34)." (PMID 32255253, 2020).
nasal polyps (4 papers, 2008 to 2022). "Nasal polyps from three patients with chronic rhinosinusitis as well as control non-polyp nasal mucosa were used to isolate and cultivate mesenchymal stem cells characterized as CD73+, CD90+, CD105+/CD14−, CD34−, and CD45−." (PMID 33287173, 2020).
PEComas (4 papers, 2013 to 2023). "With the exception of the immunohistochemical markers detailed above, the expression of other markers including CD34 and CD117 differed between PEComas." (PMID 26698563, 2015). "Otherwise, epithelioid angiomyolipoma is a member of perivascular epithelioid cell tumours (PEComas) which commonly label for HMB-45, Vimentin, and smooth muscle markers and are negative for CD34." (PMID 24490095, 2013). "Perivascular epithelioid cell tumor (PEComa) is not supported if HMB45, CD34, and SMA are negative." (PMID 29702975, 2018).